USP10 (ubiquitin specific peptidase 10)
Diseases named in the same sentence as USP10 in open-access papers (continued):
Sharing a sentence is not in itself a finding about the gene and the disease.
hepatocellular carcinoma (29 papers, 2020 to 2026). A malignant tumor that arises from hepatocytes. "In agreement with previous studies, USP10 acts as an oncoprotein in hepatocellular carcinoma, esophageal squamous cell carcinoma, glioblastoma, and acute myeloid leukemia through the stabilization of YAP, ANLN, RUNX1, and FLT3." (PMID 40605431, 2025). "Other studies have revealed that USP10 promotes the progression of hepatocellular carcinoma, esophageal squamous cell carcinoma, and glioblastoma." (PMID 40517136, 2025). "USP10 also promoted hepatocellular carcinoma proliferation by deubiquitylation and stabilization of YAP/TAZ." (PMID 35223996, 2022). "In contrast, USP10 promotes proliferation and metastasis of hepatocellular carcinoma by targeting YAP/TAZ and Smad4, respectively." (PMID 35277183, 2022). "USP10 inhibits hepatocellular carcinoma (HCC) growth in vivo by inhibiting the mTOR signaling pathway." (PMID 33277473, 2020). "In hepatocellular cancer, USP10, as a tumour suppressor, negatively regulates mTORC1 activation and AKT phosphorylation by stabilising AMPKα and PTEN in HCC cells." (PMID 33133065, 2020). "Knockdown of this expression may inhibit the proliferation and migration ability of hepatocellular carcinoma cells by regulating miR-193b-5p, which, in turn, affects ubiquitin specific peptidase 10 (USP10)." (PMID 38139458, 2023). "USP10 promotes hepatocellular cancer metastasis by stabilizing Smad4 protein." (PMID 34412625, 2021). "USP10 can directly bind to Smad4 and act on the Lys-48-linked polyubiquitin chain on Smad4 to stabilize it; USP10 regulates the abundance and function of Smad4 protein through deubiquitination and activates the TGF-β pathway to further promote the migration of hepatoma cells." (PMID 35875077, 2022). "USP10 defects improved polyubiquitination of YAP/TAZ and their proteasomal degradation in hepatocellular carcinoma." (PMID 37072811, 2023). "Depletion of USP10 enhances polyubiquitination of YAP/TAZ, promotes their proteasomal degradation, and ultimately arrests the proliferation of hepatocellular carcinoma." (PMID 37349820, 2023). "Recently, a bioinformatic study comprehensively analyzed the prognostic value and immune infiltration of USP10 in pan-cancer, especially in PDAC and hepatocellular carcinoma." (PMID 36582601, 2022). "As a consequence, inactivation of USP10 promoted YAP/TAZ ubiquitination and proteasome-mediated degradation, and inhibited hepatocellular carcinoma cell growth both in vitro and in xenografts." (PMID 33869224, 2021). "In hepatocellular carcinoma patient samples as well as in chemical-induced mouse liver cancers, USP10 expression positively correlated with YAP/TAZ abundance, and high USP10 expression correlated with poor prognosis in hepatocellular carcinoma patients." (PMID 33869224, 2021). "USP10 depletion enhanced the polyubiquitination of YAP/TAZ, promoted their proteasomal degradation, and ultimately arrested the proliferation of hepatocellular carcinoma in vitro and in vivo." (PMID 34315490, 2021). "In addition, USP10 can stabilize proliferating cell nuclear antigen (PCNA) through deubiquitination to enhance the proliferation and migration of hepatoma cells." (PMID 35875077, 2022). "For example, USP10 interacts with and stabilizes YAP/TAZ and SMAD4 to promote the proliferation of hepatocellular carcinoma, while another study indicated that USP10 inhibited the poly-ubiquitylation of AMPKα and PTEN to suppress hepatocellular carcinoma progression." (PMID 35351136, 2022).
hepatocellular carcinoma (continued). "Furthermore, in hepatocellular carcinoma, S100A9 accelerates tumor progression by recruiting ubiquitin specific peptidase 10 (USP10) and Phosphoglycerate Mutase Family Member 5 (PGMFM5) to form a trimer that facilitates mitochondrial fission and ROS production." (PMID 40630623, 2025). "Ubiquitin-specific protease 10 (USP10), which is abnormally activated in a variety of malignant tumor, can bind specifically to SMAD4 and stabilize the effect of SMAD4 by increasing its deubiquitination, and further lead to the metastasis of human hepatoma cells Bel-740286." (PMID 38385079, 2024). "For instance, USP10 and USP21 could promote hepatocellular carcinoma and non-small-cell lung cancer proliferation, respectively." (PMID 34261480, 2021).
lung carcinoma (28 papers, 2016 to 2026). "Moreover, our clinical data indicate that high levels of USP10 mRNA are associated with lower overall survival in advanced lung cancer patients who received platinum-based chemotherapy." (PMID 32382008, 2020). "USP10 functions as a tumor suppressor in lung cancer and as an oncogene in several other cancers, including CRC, HCC, and gastric cancer." (PMID 40069750, 2025). "Lung cancer has the highest rates of cancer mortality worldwide, and multiple studies have investigated the role of USP10 in lung cancer." (PMID 36248971, 2022). "As in HCC, USP10 was found to be downregulated in lung cancer, and the knockdown of USP10 inhibited PTEN ubiquitination and promoted tumor growth and invasion." (PMID 35627217, 2022). "USP10 was reported to promote the hepatocellular and lung cancer cells proliferation, but its function on ESCC remains to be elucidated." (PMID 36163081, 2022). "As for USP10, decreased expression of USP10 has been proved to be an indicator of poor prognosis in lung cancer and epithelial ovarian cancer." (PMID 33178587, 2020). "Conversely, USP10 could act as a tumor suppressor by deubiquitinating different substrates in renal cell carcinoma and lung cancer." (PMID 40517136, 2025). "In contrast, USP10 exerts a tumor suppressor effect by stabilizing KLF4 in lung cancer." (PMID 36526897, 2023). "However, the research regarding USP10 in lung cancer is still limited, and available results are also controversial." (PMID 35277183, 2022). "In colon, gastric, and lung cancer tissues, USP10 levels are decreased compared to normal tissue." (PMID 36543867, 2022). "USP10 suppresses lung cancer cell invasion and growth via upregulating PTEN." (PMID 34412625, 2021). "Moreover, USP10 inhibited cell growth and invasion in lung cancer, and was an independent factor for the prognosis of gastric carcinoma." (PMID 34335109, 2021). "USP10 promotes lung cancer xenografts growth and confers cisplatin resistance in a mouse model." (PMID 32382008, 2020). "We then set out to determine whether knockdown of USP10 sensitizes lung cancer xenografts to cisplatin." (PMID 32382008, 2020). "To investigate the role of USP10 in lung cancer, we employed a protein purification approach." (PMID 32382008, 2020). "However, in lung cancer, USP10 can inhibit cell growth and invasion by stabilizing PTEN, suggesting that the roles of USP10 in the different cancer types are distinct." (PMID 31133011, 2019). "Furthermore, USP10 inhibited lung cancer cell growth and invasion by upregulating PTEN44." (PMID 38689092, 2024). "Therefore, developing clinically relevant USP10 inhibitors could benefit lung cancer patients resistant to conventional platinum-based therapeutics." (PMID 32382008, 2020).
lung carcinoma (continued). "CONCLUSIONS: Our findings reveal a novel mechanism by which circAFF4 interacts with USP10, impairing USP10-mediated stabilization of GPX4, promoting ferroptosis in lung cancer cells, and ultimately suppressing lung cancer progression." (PMID 42010438, 2026). "Mechanistically, circAFF4 bound to the deubiquitinating enzyme USP10, which in turn suppressed USP10-mediated deubiquitination of GPX4, and enhanced the ubiquitin-dependent proteasome degradation of GPX4, thereby facilitating ferroptosis in lung cancer cells." (PMID 42010438, 2026). "A recent study reported that USP10 regulates KLF4 stability and exerts a tumor-suppressive role in lung cancer." (PMID 35277183, 2022). "In an attempt to establish the correlation between USP10 and HDAC6 expression in cancer cell lines, we examined USP10 and HDAC6 protein levels in eight lung cancer lines and nine ovarian cancer cell lines." (PMID 32382008, 2020). "The circAFF4/USP10/GPX4 axis provides a new direction and may be a potential target for lung cancer treatment." (PMID 42010438, 2026). "Moreover, review of high-density TMAs showed both USP10 and HDAC6 overexpression in ovarian and lung cancer patient samples and a positive correlation between their expression." (PMID 32382008, 2020).
gastric cancer (19 papers, 2018 to 2026). A primary or metastatic malignant neoplasm involving the stomach. "USP10 deubiquitinates of YBX1 leading to increased apoptosis in gastric cancer cells and decreased resistance to oxaliplatin." (PMID 39605891, 2024). "Previously, we reported that the expression of USP10 was negatively correlated with the depth of gastric wall invasion, lymph node metastasis, and prognosis in gastric cancer (GC) patients." (PMID 38937694, 2024). "Together, these findings suggested that LINC00240 promotes DDX21 stabilization via intensifying interactions between DDX21 and its novel deubiquitinase USP10 in gastric cancer." (PMID 37072811, 2023). "We also found that LINC00240 interacts with oncoprotein DDX21, suppresses its ubiquitination and stabilize the protein via intensifying binding of DDX21 with its novel deubiquitinase USP10, which, thus, leading to disease progression of gastric cancer." (PMID 37072811, 2023). "By contrast, USP10 expression is downregulated in other malignancies including gastric carcinoma, lung, and colon cancers." (PMID 37371055, 2023). "We demonstrated that abnormal expression of USP10 is related to tumorigenesis in various types of cancer, including liver, lung, ovarian, breast, prostate, and gastric cancers and acute myeloid leukemia." (PMID 36248971, 2022). "USP10 expression is downregulated in some cancers, including gastric cancer and NSCLC." (PMID 36969062, 2023). "Downregulation of USP10 results in a poor prognosis and shortened survival in gastric cancer." (PMID 36969062, 2023). "In contrast, more USP10 protein could be precipitated with DDX21 in the stably LINC00240-OE cells compared to the control gastric cancer cells." (PMID 37072811, 2023). "Importantly, LINC00240 could interact and stabilize oncoprotein DDX21 via eliminating its ubiquitination by its novel deubiquitinating enzyme USP10, which, thereby, promote gastric cancer progression." (PMID 37072811, 2023). "Endogenous DDX21 could also be precipitated with USP10 in both gastric cancer cell lines." (PMID 37072811, 2023). "Importantly, LINC00240 could interact and stabilize oncoprotein DDX21 via eliminating its ubiquitination by its novel deubiquitinating enzyme USP10, which, thereby, promote progression of gastric cancer." (PMID 37072811, 2023). "Long noncoding RNAs LINC00240 interacted with DDX21 and stabilized DDX21 protein by preventing USP10-mediated DDX21 ubiquitination and subsequent degradation, leading to enhanced growth and metastasis of gastric cancer cells." (PMID 39866844, 2025). "Complementing these findings, the role of ubiquitin-specific peptidase 10 (USP10), a member of the ubiquitin-specific protease family involved in stress responses, tumor growth, and cellular metabolism, has been investigated in gastric cancer (GC)." (PMID 41458541, 2025). "In summary, we revealed the importance of LINC00240 transcribed from the 6p22.1 locus in gastric cancer and uncovered a novel regulatory partnership between LINC00240 and USP10 in controlling ubiquitination of oncogenic protein DDX21." (PMID 37072811, 2023). "After knock-downing of USP10 expression, obviously decreased DDX21 protein levels could be detected in gastric cancer cells in comparation with the control cells." (PMID 37072811, 2023). "Moreover, USP10 expression in gastric carcinoma tissues was lower than that in non-cancerous mucosa tissues, and was an independent prognostic factor for the overall survival in gastric carcinoma." (PMID 36949071, 2023).
prostate carcinoma (19 papers, 2015 to 2026). A carcinoma that arises from epithelial cells of the prostate gland. "High expression of USP10 is also significantly associated with poor prognosis in prostate cancer patients." (PMID 33277473, 2020). "Studies have shown that USP10 is strongly expressed in various tumor tissues, including hepatic, breast, and prostate cancer." (PMID 37184153, 2023). "USP10 can also induce epithelial–mesenchymal transition (EMT) in prostate cancer via deubiquitination of substrate proteins." (PMID 37184153, 2023). "Concurrently, USP10 overexpression is also observed in advanced prostate cancer patients and overexpression correlates with poor patient outcomes." (PMID 33277473, 2020). "In prostate cancer, with increasing grade of disease, the cellular localisation of Usp10 changes with expression becoming predominantly nuclear allowing for higher activity towards H2A.Z." (PMID 25962961, 2015). "In prostate cancer, high expression of USP10 indicates poor prognosis." (PMID 35627217, 2022). "Moreover, genetic alterations in USP10 might play an important role in the genomes of endometrial and prostate cancers." (PMID 35433424, 2022). "Interestingly in prostate cancer with increased cancer grade and metastasis the expression of Usp10 becomes predominantly nuclear which could possibly be associated with elevated DNA damage." (PMID 25962961, 2015). "Moreover, spautin-1 suppresses the survival of ovarian cancer, prostate cancer, melanoma, and NSCLC cells in a USP10-independent manner." (PMID 35627217, 2022). "Interestingly, spautin-1 also inhibits the proliferation of prostate cancer, NSCLC, ovarian cancer, and melanoma cells in a USP10-independent manner." (PMID 36248971, 2022). "In addition, USPs (ubiquitin-specific protease) amplification has been reported in prostate cancer, such as USP2a, USP7, and USP10." (PMID 32784507, 2020). "Even though the role of USP10 in prostate cancer has not been investigated, it is interesting to note that USP10 is also involved in the regulation of the androgen receptor." (PMID 25605410, 2015).